HID1 (HID1 domain containing)
Description:
Plays a role in the biogenesis of large dense core vesicles (LDCVs) at the trans-Golgi network; necessary for the proper sorting of cargo into LDCVs and is required for proper regulated exocytosis (also known as regulated secretory pathway).
Synonyms: C17orf28; DMC1; HID-1; 17orf28; DEE105
Tractability: PROTAC: its protein half-life has been measured.
Gene: Protein-coding gene on chromosome 17 (74,950,741 to 74,973,166, reverse strand). Ensembl gene ENSG00000167861.
Subcellular location: Cytoplasm; Golgi apparatus, trans-Golgi network membrane
Subcellular location (Human Protein Atlas): Cytosol; Golgi apparatus
Gene Ontology:
Molecular function: protein binding
Biological process: dense core granule biogenesis
Cellular component: cytoplasm; cytoplasmic microtubule; cytoplasmic side of Golgi membrane; cytosol; extracellular exosome; Golgi apparatus; Golgi medial cisterna; Golgi trans cisterna; membrane; trans-Golgi network membrane
Genetic constraint (gnomAD): Loss-of-function variants: 38 observed, 77.55 expected, observed/expected ratio (o/e) 0.49, 90% interval 0.38 to 0.64. The upper end of that interval is the gene's LOEUF score, 0.64, which puts it in group 2 of 6, group 1 being the genes least tolerant of losing a copy. Missense variants: 852 observed, 994.59 expected, observed/expected ratio (o/e) 0.86, 90% interval 0.81 to 0.91. Synonymous variants: 442 observed, 403.15 expected, observed/expected ratio (o/e) 1.1, 90% interval 1.01 to 1.19.
Homologues: Orthologues: chimpanzee HID1 (99% identical), macaque HID1 (99% identical), pig HID1 (96% identical), mouse Hid1 (96% identical), rat Hid1 (95% identical), dog HID1 (94% identical), guinea pig HID1 (93% identical), tropical clawed frog hid1 (79% identical), Drosophila melanogaster CG8841 (66% identical), Caenorhabditis elegans hid-1 (55% identical), zebrafish hid1a (19% identical).
Diseases named in the same sentence as HID1 in open-access papers:
HID1 is named in the same sentence as 11 diseases in open-access papers, as found by Europe PMC text mining. Sharing a sentence is not in itself a finding about the gene and the disease. The quoted sentences say what the papers report.
Obesity (2 papers, 2022 to 2024). Accumulation of substantial excess body fat. "Previous RNA-Seq transcriptomic studies found that HID1 mRNA levels were significantly correlated with obesity and glucose metabolic parameters in human subcutaneous and adipose tissues after Bonferroni correction for multiple testing." (PMID 38184583, 2024).
asthenozoospermia (1 paper, 2020). "Subsequent Sanger sequencing on genomic DNA from all the available family members (III:1, III:2, and IV:1–7) verified four variants in four genes (DNAH17, GPS1, HID1, and USP36) recessively coinherited with asthenozoospermia." (PMID 31658987, 2020).
Epileptic encephalopathy (1 paper, 2025). A condition in which epileptiform abnormalities are believed to contribute to the progressive disturbance in cerebral function. "documented six patients from five unrelated families with biallelic HID1 variants who exhibited combined pituitary hormone deficiency and epileptic encephalopathy." (PMID 40704143, 2025).
Glucose intolerance (1 paper, 2016). Glucose intolerance (GI) can be defined as dysglycemia that comprises both prediabetes and diabetes. "Loss of function of HID-1 in mice leads to diabetes-like symptoms characterized by glucose intolerance, insufficient insulin release, and elevated proinsulin secretion." (PMID 27751232, 2016). "At 10–12 weeks of age, Hid1-betaKOmice exhibited higher basal glucose levels and glucose intolerance than RIP-Cre mice during glucose-tolerance testing (GTT)." (PMID 27751232, 2016). "A conditional knockout of HID-1 in pancreatic β cells leads to glucose intolerance and a remarkable increase in the serum proinsulin/insulin ratio caused by defective proinsulin processing." (PMID 27751232, 2016).
tumor (5 papers, 2010 to 2019). "Furthermore, the identified hub genes of the individual GRNs, e.g., HID1/DMC1 (tumor development), RNF17/TDRD4 (cancer antigen) and CYP4A11 (angiogenesis/ metastasis) are known cancer associated markers." (PMID 25971253, 2015).
cancer (3 papers, 2015 to 2021). A tumor composed of atypical neoplastic, often pleomorphic cells that invade other tissues. "The loss of function of HID1 is known to be associated with the development of cancer." (PMID 34674656, 2021). "HID1 gene encodes a protein functioning in the trafficking of cargos that are important for the sorting/biogenesis/maturation of dense core vesicles and plays an important role in the development of cancers in a broad range of tissues." (PMID 31244774, 2019). "We identified hub genes such as HID1 (RNAseq) RNF17 (TDRD4) (Bead), CYP4A11 (Oligo) for the individual GRNs which show in the literature strong evidence for cancer related diagnostic and prognostic properties." (PMID 25971253, 2015). "HID1 and RND3 are known to be downregulated in various cancers." (PMID 34674656, 2021).
HID1 also shares sentences with these, for which no sentence is quoted: gastric cancer (1 paper); hyperinsulinism (1); Hypoglycemia (1); lung carcinoma (1); pituitary hormone deficiency (1).